GSK3B (glycogen synthase kinase 3 beta)
Diseases named in the same sentence as GSK3B in open-access papers (continued):
Sharing a sentence is not in itself a finding about the gene and the disease.
colon carcinoma (continued). "The pro-inflammatory cytokine, Interleukin 1β (IL-1β), phosphorylates and inactivates GSK3β, enhancing Wnt signalling mediated transcription of β-catenin target genes in colon cancer." (PMID 38136392, 2023). "In ovarian cancer cells, emodin inhibited the EMT process through the ILK/GSK-3β/Slug signaling pathway, while in colon cancer cells, emodin inhibited cell invasion and migration by suppressing EMT via the Wnt/β-catenin pathway." (PMID 37446730, 2023). "For example, it has been reported that knockout of ISOC1 activates the AKT1/GSK-3β pathway and induces the apoptosis of colon cancer cells." (PMID 36144632, 2022). "We filtered four genes (BDNF, PTGS2, CTNNB1, and GSK3B) from the colon tumor and matched normal RNA-seq data, estimated the differences in fold change, and performed a t-test to determine the p value representing significant differences." (PMID 35054980, 2022). "The knockout of 4-1BBL, the ligand of 4-1BB, promotes the accumulation of Gsk3β in the nucleus of colon cancer cells and inhibits the expression of Wnt signal pathway-related genes, inhibiting the proliferation of colon cancer cells." (PMID 36358792, 2022). "Accordingly, Wnt ‘super-activation’ by GSK3β inhibition (i.e., Chiron) in the APC/CTNNB1-mutated colon cancer cell lines results in a significant expansion of EpCAMlo cells and increased ZEB1 expression." (PMID 34036938, 2021). "Some studies revealed that treating colon cancer cell lines with various concentrations of the GSK-3β inhibitors reduced the viability of cells and stimulated apoptotic machinery in a dose-dependent way." (PMID 34069111, 2021). "In the present study, we found that GSPT1 negatively regulated the GSK-3β signaling pathway in colon cancer cells." (PMID 33819920, 2021). "GSK-3β negotiates the nuclear factor-ҡ (NF-ҡB) pathway and so it plays a vital role in cell survival specifically in colon cancer in which there is coactivation for both Wnt/β-catenin and NF-ҡB pathways through ubiquitin system dysregulation." (PMID 34069111, 2021). "Among them, Resveratrol inhibits the invasion and metastasis of colon cancer through reversal of EMT via the AKT/GSK-3β/Snail signaling cascade." (PMID 33762939, 2021). "In vitro study revealed that GSK3β was positively correlated with colon cancer cells’ survival, and their higher expression levels were unexpectedly associated with enhanced Hh-GLI signaling." (PMID 34572373, 2021). "Our data suggest that 36-077 promotes the efficacy of 5-FU treatment in killing colon cancer cells by modulating the GSK-3β/Wnt/β-catenin signaling, further emphasizing the translational potential of this inhibitor for improving colon cancer therapy." (PMID 33946505, 2021). "In the current study, Wnt/β-catenin/GSK-3β proteins were upregulated in the in vivo chemically induced colon cancer in mice." (PMID 34069111, 2021). "In the in vivo colon cancer experiment, nitazoxanide triggered a dose-dependent repression in Wnt/β-catenin/GSK-3β protein production." (PMID 34069111, 2021). "In order to investigate the relationship between GSPT1 and GSK-3β in colon cancer cells, the expression of GSK-3β was up-regulated after GSPT1 was silenced in HCT116 cells." (PMID 33819920, 2021). "A role for the GSK-3β/Wnt/β-catenin signaling in promoting colon cancer malignancy including CSCs is well documented." (PMID 33946505, 2021). "Oridonin isolated from Rabdosia rubescens is reported to inhibit the proliferation and induced apoptosis in colon cancer COLO205 cells by decreasing the phosphorylation of GSK-3β." (PMID 32093300, 2020).
colon carcinoma (continued). "Previous studies have suggested that hesperidin induces apoptosis and autophagy through inhibition of PI3K/Akt/mTOR and glycogen synthase kinase-3 beta (GSK-3β) pathways in colon cancer." (PMID 31815144, 2019). "Taken together, these data suggest that JSD can reverse EMT and inhibit colon cancer metastasis through the AKT/GSK-3β signaling pathway in vitro and in vivo." (PMID 31772677, 2019). "The previous studies have suggested that hesperidin induces apoptosis and autophagy through inhibition of the PI3K/Akt/GSK-3β/mTOR pathway in colon cancer." (PMID 31815144, 2019). "Together, these results indicated the therapeutic response to SC66 is through Akt/GSK-3β/Bax axis, which served GSK-3β as a potential biomarker for colon cancer therapy." (PMID 31168297, 2019). "A recent study indicated that regorafenib induced colon cancer cell apoptosis via GSK-3β/Mcl-1 axis." (PMID 31168297, 2019). "The biological role of GSK-3β in colon cancer growth suppression induced by SC66 was detected in vitro and in vivo." (PMID 31168297, 2019). "CDX2 transactivates the expression of GSK-3β and Axin2 to inhibit the cell proliferation and tumor formation in colon cancer." (PMID 31200542, 2019). "We were interested in determining if Fap1-inhibition activated Fas or Gsk3β in CD133+ colon cancer stem cells." (PMID 29899829, 2018). "Efficiency of the two GSK3β inhibitors and GSK3β-specific siRNA was variable among the colon cancer cells examined in this study." (PMID 29568361, 2018). "Consistently, the role of TRPM4 in the regulation of β‐catenin signaling through GSK‐3β has been described in a colon cancer cell study." (PMID 28614631, 2018). "ILK1 can regulate β-catenin-dependent expression of Snail in human colon carcinoma cells, and GSK-3β manipulates the expression of Snail and β-catenin during Fas-induced EMT." (PMID 29290941, 2017). "We showed that alcohol activated Wnt/GSK3β/β-catenin pathway in colon cancer cells, resulting in an increase in the migration/invasion of colon cancer cells." (PMID 29156633, 2017). "The fact that WBR downregulates GSK3β and produces better colon tumor inhibition suggests that other mechanisms are involved in WBR's anti-colon cancer properties and are likely modulated by NF-κB." (PMID 28210630, 2017). "Taken together, these results indicate that DDA1 promotes the progression of stage IIB–IIC colon cancers by activating the NFκB/CSN2/GSK-3β pathway." (PMID 26942699, 2016). "GSK3β expression is known to be induced in several cancer types, which include colon cancer, pancreatic cancer, prostate cancer and glioblastoma." (PMID 27602497, 2016). "In summary, DDA1 promotes the progression of stage II colon cancer through the activation of the NFκB/CSN2/GSK3β pathway." (PMID 26942699, 2016). "Lithium reduces the expression of TGFBIp in SW620 colon cancer cells by inhibiting the transforming growth factor β1-Smad3 signaling pathway via GSK3β inactivation." (PMID 26857144, 2016). "Lithium reduces the expression of transforming growth factor-β-induced protein (TGFBIp) in colon cancer cells by inhibiting Smad3 phosphorylation via GSK3β inactivation." (PMID 26857144, 2016). "OLA1-KD tumors in the H116 colon cancer model showed markedly decreased eIF2α at Ser-51 (eIF2α-p) and reduced GSK3β-p, indicating hypoactive ISR and hyperactive GSK3 signaling." (PMID 26655089, 2016). "An involvement of GSK3β in mediating tumorigenic pathways is also indicated by its induced expression in various cancers including colon cancer, pancreatic cancer, prostate cancer, and glioblastoma." (PMID 27602497, 2016). "On the contrary, studies in colon cancer cells showed that either pharmacological inhibition or siRNA-mediated knockdown of GSK3β augmented TZD-induced reduction of NFκB activity, cell growth inhibition and apoptosis induction." (PMID 27602497, 2016).
colon carcinoma (continued). "In glioblastoma cells, GSK3β phosphorylation was shown to be reduced, leading to β-catenin phosphorylation similarly to the effects observed in the colon cancer cells." (PMID 27429001, 2016). "Treatment with LiCl or transfection with DNGSK3β rescued effectively the intracellular β-catenin/TCF transcriptional activity inhibited by Z86, indicating that Z86 inhibited Wnt signaling through activation of GSK3β in colon cancer cells." (PMID 27551464, 2015). "Our results provide functional and mechanistic links between Hes1 and Bmi-1/PTEN/Akt/GSK3β signaling in the development and progression of colon cancer." (PMID 26452029, 2015). "Here, results indicated that Hes1 downregulated PTEN, and promoted Akt activation and GSK3β phosphorylation in colon cancer cells." (PMID 26452029, 2015). "It was reported that DLC1 inhibited the growth and invasion of colon cancer cells through the Wnt/β-catenin signaling pathway by upregulating GSK-3β, and downregulating β-catenin." (PMID 26223867, 2015). "On the other hand, a previous study on colon cancer cells reported that the K-ras oncoprotein transactivates β-catenin via inactivation of GSK3β." (PMID 26556864, 2015). "Galectin-3 can also mediate nuclear β-catenin accumulation by regulating glycogen synthase kinase-3β (GSK-3β) activity in colon cancer." (PMID 25669973, 2015). "In this study, for the first time, we present evidence that pharmacological inhibition of GSK-3β by lithium treatment can inhibit colon cancer cell line SW480 survival and proliferation in a dose and time-dependent pattern." (PMID 25002914, 2014). "From the common edible plants 11 were found to have compounds targeting 3 proteins (MARK1, SMAD3, GSK3B) of the KEGG colon cancer pathway and 28 targeting the remaining 9, which are first-degree neighbors of the proteins in the KEGG colon cancer pathway." (PMID 24886433, 2014). "The selective GSK3β inhibitor lithium has been reported to promote the motility of colon cancer cells, whereas treating cultured cells with GSK3 inhibitors or small interfering RNA (siRNA) targeting GSK3 has been reported to inhibit motility." (PMID 24618715, 2014). "Accordingly, the downregulation of GSK3β inhibits proliferation and enhances apoptotic cell death in chronic lymphocytic leukemia B cells, renal cancer cells, pancreatic cancer cells, and colon cancer cells." (PMID 23527181, 2013). "Butyrate also increases the differentiation of human LIM2537 colon cancer cells, decreases GSK-3β activity and increases levels of both membrane-bound and Apc/axin/GSK-3β complex-associated pools of β-catenin." (PMID 23593331, 2013). "Galectin-3 upregulates β-catenin expression, increases its nuclear accumulation, and augments Wnt/β-catenin signaling in human colon cancer cells by regulating glycogen synthase kinase-3β (GSK-3β) phosphorylation and activity via the PI3K/Akt pathway." (PMID 24303084, 2013). "We show for the first time that the silencing of galectin-3 sensitizes MDR cells to epirubicin by inhibiting ABC transporters and activating the mitochondrial pathway of apoptosis through modulation of the β-catenin/GSK-3β pathway in human colon cancer cells." (PMID 24303084, 2013).
colon carcinoma (continued). "We recently reported that colon tumor cells stimulate macrophages to release IL-1β, which in turn inactivates GSK3β and enhances Wnt signaling in colon cancer cells, generating a self-amplifying loop that promotes the growth of tumor cells." (PMID 20661477, 2010). "We showed that pharmacological inhibition of GSK3β or IL-1β mediated inhibition of GSK3β, were sufficient to elevate the levels of Snail in colon cancer cells." (PMID 20661477, 2010). "Similarly, IL-1β enhances colon cancer cell proliferation by inhibiting GSK3β, thereby activating the Wnt pathway and culminating in tumorigenesis." (PMID 40019680, 2025). "SD treatment significantly down‐regulated p‐PI3K, PI3K, p‐AKT, AKT, mTOR, p‐GSK3β, and β‐catenin while up‐regulating GSK3β and p‐β‐catenin, suggesting that SD may inhibit colon cancer cell growth by regulating AKT/GSK3β/β‐catenin signaling pathway." (PMID 39155844, 2024). "Furthermore, EndMT, PECAM-1 and Akt/GSK-3β/β-catenin signaling were analyzed under high glucose (HG) and human colon cancer cell (HCCC) supernatant (SN) or coculture conditions by western and immunofluorescence tests." (PMID 37580771, 2023). "Thus, there is an increase in E cadherin expression and a decrease of N cadherin, phospho (p)-AKT1, p-GSK3β, and Snail in colon cancer." (PMID 37108477, 2023). "Furthermore, galectin-3 mediates the Wnt signaling pathway and nuclear β-catenin accumulation by regulating glycogen synthase kinase-3β (GSK3B) activity in human colon cancer cells." (PMID 37185758, 2023). "We showed that GSK3α and GSK3β differ greatly in their binding proteins and phospho-substrates in colon cancer cells, although we cannot exclude the possibility that the phospho-substrates of GSK3α and GSK3β may differ in different cell types." (PMID 37031867, 2023). "A previous study showed that interleukin-1β, released by TAMs, might enhance the presence of β-catenin through GSK3β phosphorylation in colon cancer cells, thereby preventing the β-catenin destruction complex from performing its normal functions." (PMID 36275697, 2022). "In addition, CCR2—the most common receptor for CCL2 —promotes stabilization and translocation of β-catenin via AKT/GSK3β signaling in colon cancer cells." (PMID 35562953, 2022). "Notable examples include Glycogen synthase kinase 3β (GSK3β), as a high throughput screen of 99 anti-cancer compounds determined that GSK3β inhibition cooperated with PARP inhibitors in colon cancer, suppressing HR and increasing both replication stress and DNA double-strand breaks." (PMID 35205643, 2022). "Intriguingly, treating colon cancer cell lines with lithium chloride, a GSK3β inhibitor, increased Ser9 phosphorylation of GSK3β, which in turn restored the balance between the activating Tyr216 and inactivating Ser9 phosphorylation on GSK3β and restored its proper function." (PMID 34572373, 2021). "The Wnt/β-catenin signaling was abnormally overexpressed in colorectal cancer and SW480 colon cancer cells; however, tea polyphenols administration effectively inhibited the Wnt/β-catenin signaling pathway to reduce the proliferation of colon cancer cells by activating the GSK3β gene." (PMID 33664749, 2021). "As a matter of fact, several findings confirmed how immune cells may regulate the Wnt pathway such as TAM that secrete interleukin-1 and phosphorylates glycogen synthase kinase 3 beta (GSK3b) and then increase the availability of β-catenin in colon cancer." (PMID 34072037, 2021). "One study reported that hesperidin treatment could induce apoptosis and trigger autophagy by inhibiting the aurora-a mediated PI3K/Akt/mTOR and glycogen synthase kinase 3 beta (GSK-3β) pathway in colon cancer mouse model." (PMID 34830339, 2021). "SC66 inhibited colon cancer cell proliferation through AKT/GSK-3β/Bax axis in vivo and in vitro." (PMID 32848734, 2020).
colon carcinoma (continued). "A recent report suggested that CaSR suppresses the malignant behavior of colonic cancer cells by regulating the Wnt signaling pathway including GSK3β and Cyclin D1, which was proved to be vitally important in the development and the growth of LUAD in previous studies, including ours." (PMID 32671062, 2020). "More recently, GSK3β is studied as a promising target for anti-cancer treatment with supporting preclinical data in a number of malignancies, including pancreatic cancer, colon cancer, bladder cancer, kidney cancer, and melanoma." (PMID 32850361, 2020). "Additionally, N-glycosylation of PDL1 further protects PDL1 from GSK3β dependent phosphorylation in breast cancer, melanoma and colon cancer models." (PMID 32850361, 2020). "Therefore, we concluded that the JSD-induced inhibition effects on colon cancer liver metastasis were realized by AKT1/GSK-3β signaling activation." (PMID 31772677, 2019). "Therefore, the TREM2-mediated Wnt/ERK/GSK-3β signaling pathway inhibited the metastasis of HT29 colon cancer cells." (PMID 31489935, 2019). "Our results provide a rational basis for the development of targeting-GSK-3β, which may serve as a potential biomarker and yield meaningful benefits for colon cancer patients in the future." (PMID 31168297, 2019). "Furthermore, our study demonstrated that CDX2 specifically and directly binds to the GSK-3β promoter and the Axin2 upstream enhancer in colon cancer cells, by qChIP." (PMID 30631044, 2019). "Therefore, it can be concluded that JSD-induced reversion of EMT in colon cancer is realized by the activation of AKT1/GSK-3β signaling." (PMID 31772677, 2019). "To achieve this, we tested a GSK3β-specific siRNA on colon cancer cells." (PMID 29568361, 2018). "Although the efficiency of the two GSK3β inhibitors (AR-A014418 and SB-216763) on several cellular processes was different, these inhibitors exerted the same pharmacological effect impairing the mitotic process of the respective colon cancer cell lines." (PMID 29568361, 2018). "This clinical study suggests that GSK3β inhibition may also attenuate cell viability and proliferation in primary colon cancer cells." (PMID 29568361, 2018). "Moreover, in murine embryonic fibroblasts and human colon carcinoma cells GSK-3β dependent phosphorylation of GLI3 leads to processing into its transcriptional repressor form GLI3R." (PMID 28575066, 2017). "In our previous study, we showed for the first time that the treatment of siRNA against galectin-3 sensitized MDR cells to Epi by inhibiting P-gp and MRPs and the activation of the mitochondrial apoptosis pathway through modulation of the β-catenin/GSK-3β pathway in human colon cancer Caco-2 cells." (PMID 28968471, 2017). "Interestingly, our results show a significant downregulation of TGFBIp expression in colon cancer cells following lithium treatment, and further demonstrate that lithium induces this effect by inhibiting Smad3 phosphorylation though GSK3β inactivation." (PMID 26857144, 2016). "Previous study reported that GSK-3β promotes NF-κB activity in colon cancer." (PMID 27302922, 2016). "For instance, in U2OS (human osteosarcoma) cells, the accumulation of the PHD2 and PHD3 proteins by hypoxia led to accelerated HIF-1 degradation after reoxygenation, while HIF-1 translation in RKO (human colon carcinoma) cells was inhibited by a decrease in GSK3β under prolonged hypoxia." (PMID 25823824, 2015). "Inhibition of GSK-3β enhances reovirus-induced apoptosis in colon cancer cells." (PMID 25370813, 2014).